FAM43A (family with sequence similarity 43 member A)
Synonyms: FLJ90022
Tractability: No criterion of Open Targets' tractability assessment is met for any kind of drug.
Gene: Protein-coding gene on chromosome 3 (194,685,883 to 194,689,037, forward strand). Ensembl gene ENSG00000185112.
Subcellular location (Human Protein Atlas): Vesicles
Gene Ontology:
Molecular function: protein binding
Genetic constraint (gnomAD): Loss-of-function variants: 13 observed, 14.14 expected, observed/expected ratio (o/e) 0.92, 90% interval 0.6 to 1.46. The synonymous counts are far from expectation, so gnomAD's model fits this gene poorly and the ratio says little. Missense variants: 573 observed, 499.33 expected, observed/expected ratio (o/e) 1.15, 90% interval 1.07 to 1.23. Synonymous variants: 319 observed, 230.37 expected, observed/expected ratio (o/e) 1.38, 90% interval 1.26 to 1.52.
Homologues: Orthologues: chimpanzee FAM43A (99% identical), pig FAM43A (92% identical), rat Fam43a (90% identical), mouse Fam43a (89% identical), guinea pig FAM43A (88% identical), rabbit FAM43A (85% identical), dog FAM43A (78% identical), tropical clawed frog fam43a (61% identical), zebrafish fam43a (61% identical), Drosophila melanogaster CG8312 (28% identical), Caenorhabditis elegans F52D10.2 (22% identical), Drosophila melanogaster CG42673 (16% identical), and 7 more. Paralogues in human: FAM43B (35% identical), NUMBL (15% identical), NOS1AP (14% identical), NUMB (14% identical), LDLRAP1 (13% identical), DAB1 (12% identical), DAB2 (12% identical), MAPK8IP1 (11% identical), MAPK8IP2 (10% identical), GULP1 (5% identical), C1orf226 (4% identical).
Diseases named in the same sentence as FAM43A in open-access papers:
FAM43A is named in the same sentence as 7 diseases in open-access papers, as found by Europe PMC text mining. Sharing a sentence is not in itself a finding about the gene and the disease. The quoted sentences say what the papers report.
triple-negative breast carcinoma (3 papers, 2023 to 2025). An invasive breast carcinoma which is negative for expression of estrogen receptor (ER), progesterone receptor (PR), and human epidermal growth factor receptor 2 (HER2). "Family with sequence similarity 43 member A (FAM43A) can predict the prognosis of triple-negative breast cancer." (PMID 38662077, 2024). "Family with sequence similarity 43 member A (FAM43A) is a protein coding gene and can predict the prognosis of triple-negative breast cancer." (PMID 37025597, 2023). "FAM43A is hypothesized to potentially serve as a new prognostic biomarker and therapeutic target for diseases such as sepsis or triple-negative breast cancer." (PMID 41229886, 2025).
Sepsis (2 papers, 2024 to 2025). Sepsis is defined as life-threatening organ dysfunction caused by a dysregulated host response to infection. "We further explored the diagnostic ability of CD160, CX3CR1, DENND2D and FAM43A for sepsis in both training cohort and test cohort." (PMID 38263335, 2024). "The ROC curve results displayed that the AUCs of CD160, CX3CR1, DENND2D and FAM43A were 0.965, 0.986, 0.991 and 0.985 in the training cohort, and 0.773, 0.756, 0.660 and 0.721 in the test cohort, indicating a favorable diagnostic ability for sepsis." (PMID 38263335, 2024). "We selected four MAAGs—CD160, CX3CR1, DENND2D, and FAM43A—to construct a prognostic model for sepsis." (PMID 38263335, 2024). "To further validate the diagnostic capability of the four genes CD160, CX3CR1, DENND2D, and FAM43A in clinical samples, we collected the 10 pairs clinical samples from the healthy and sepsis samples." (PMID 38263335, 2024). "The qRT-PCR results exhibited that the mRNA expression of CD160, CX3CR1, DENND2D and FAM43A were obviously down-regulated in the sepsis group which was consisted with previous results." (PMID 38263335, 2024). "Unlike FAM43A, ample research exists on CX3CR1’s role in sepsis." (PMID 38263335, 2024).
asthma (1 paper, 2025). "Among these associations, we observed a decreased expression of FAM43A with increased methylation of cg02072170, and this gene is associated with eosinophil counts and thus associated with asthma etiology." (PMID 40349045, 2025).
sarcopenia (1 paper, 2025). Progressive decline in muscle mass due to aging which results in decreased functional capacity of muscles. "From a clinical perspective, the potential of ENSA, FAM43A, MDH2, NUBP1, SAMM50, and TM2D1 as biomarkers is promising, as they may be measurable in peripheral blood or muscle biopsy specimens to support early screening and individualized diagnosis of AS patients at risk of sarcopenia." (PMID 41204493, 2025).
FAM43A also shares sentences with these, for which no sentence is quoted: cancer (1 paper); epithelial ovarian cancer (1); serous ovarian cancer (1).